IL17A (interleukin 17A)
Diseases named in the same sentence as IL17A in open-access papers (continued):
Sharing a sentence is not in itself a finding about the gene and the disease.
colitis (continued). "Like IL-17A knockout mice, mice lacking IL-22 develop severe colitis following oral DSS administration as compared to wild-type mice." (PMID 22082127, 2011). "Further, in the CD45RBhi CD4+ T cell transfer model of colitis, IL-17A mediated protection, rather than inducing inflammation." (PMID 21060867, 2010). "Moreover, the adaptor protein CARD9 was critical in PMA1-containing EV-induced colitis, and CARD9-deficient DCs did not induce TH17 cell differentiation or IL-17A production." (PMID 39886799, 2025). "To gain a deeper understanding of the mechanism by which TP2 alleviates colitis, we utilized ELISA technology to assess typical pro-inflammatory and anti-inflammatory cytokines in rats’ colonic tissues, including TNF-α, IFN-γ, IL-1β, IL-6, IL-10, IL-17A, IL-22, and IL-23." (PMID 39776580, 2024). "Moreover, another study also proposed that ginsenosides Rd was able to effectively alleviate DSS colitis in mice through inhibiting proinflammatory cytokines expression (TNF-α, IFN-γ, IL-6, IL-12/23p40, and IL-17A) and inhibiting NF-κB and P38MAPK signaling pathways." (PMID 38698858, 2024). "Additionally, we observed an increase in the population of IL-17A-producing Th17 cells in MLNs when mPGES-1 is absent, suggesting that Th17 differentiation and expansion during colitis is modulated by an mPGES-1-dependent mechanism." (PMID 39596393, 2024). "IL-17F (closest in sequence homology to IL-17A), but not IL-17A, can reduce the presence of Treg-inducing Clostridium cluster XIVa in colonic microbiota, and IL-17F drives intestinal pathology in a T-cell transfer mouse model of colitis." (PMID 38567051, 2023). "Similarly, HS intake in mice resulted in an enhanced inflammatory response in terms of cytokine production (pro-inflammatory TNF-α, IL-17A, and IL-23), increased IL-23R+CD4 T cells, MAP, and exacerbated colitis in mice with artificially induced inflammatory bowel disease (IBD)." (PMID 37108475, 2023). "Indeed, the tumor infiltration of the stem-like subset, not the terminal subset, reduced significantly in the colitis mice with abnormal IL-17A generation." (PMID 37605139, 2023). "In addition, studies have reported that intraperitoneal injection of derivatives of oridonin at 5 mg/kg or 7.5 mg/kg in a mouse colitis model can improve colitis via reducing the expression of Th1/Th17, TNF-α, IFN-γ, and IL-17A and inhibiting the expression of NF-kB (p65), thereby improving colitis." (PMID 36894905, 2023). "However, DSS-colitis was shown to be independent of the production of IL-17 within lamina propria CD4+ T cells, where neutralisation of IL-17A in prototypical Th2 biased BALB/c mice aggravated disease." (PMID 36012618, 2022). "Although the Th17-cell subset is most prominently associated with IL-23R function, our recent work suggests that the immunopathology driven by Red 40 and IL-23 does not depend on classical Th17 responses, as blocking IL-17A and IL-17F fails to prevent colitis development in R23FR mice." (PMID 35468944, 2022). "Furthermore, increased sensitivity to DSS-induced colitis was observed in Traf5-/- mice, and might be attributed to enhanced Th2 and IFN-γ/IL-17A co-producing CD4+T cell responses and CD4+T cell NF-κB activation under intestinal inflammation." (PMID 34956195, 2021). "We found that the absence of IL-17A tended to attenuate acute colitis." (PMID 31941937, 2020). "Additionally, intraperitoneal injection of mice with recombinant RELMα increased C. rodentium-induced colitis, including increased IL-17, whereas IL-17A−/− mice did not display increased colitis in response to RELMα treatment." (PMID 32508838, 2020). "However a vast majority of these studies have only investigated the role of IL-17A in the context of colitis and not acute in small bowel inflammation." (PMID 32676080, 2020). "In the absence of IL-17A, increased tissue damage was observed in the colorectum of colitis mice." (PMID 32391010, 2020).
colitis (continued). "Although neutralization of IL-17A was not effective in the relief of colitis in a mouse model or in a clinical study of CD patients, another Th17-type cytokine, IL-21, also has pro-inflammatory effects and may be a suitable therapeutic target." (PMID 31767028, 2019). "Indeed, GSK343 administration led to a profound decrease in the levels of pro-inflammatory cytokines, including IL-6 and IL-1β, whereas the levels of TNF-α and IL-17A remained unaffected, indicating that GSK343 treatment reduces the inflammatory response during DSS-induced colitis." (PMID 31160593, 2019). "Furthermore, anti-IL17A treatment failed to attenuate colitis induced by adoptive transfer of Tbx21−/− CD4 T cells in Rag1−/− recipients." (PMID 29416538, 2018). "This is not surprising, as one could expect that by protecting mice from developing colitis, BI119 would be acting not only against direct targets of RORγt (such as IL17A), but also on the expression of indirect targets (IFNG or S100A8) associated with the inflammatory response in colitis." (PMID 30405600, 2018). "In several other homeostatic models, where CD103+CD11b+ DCs were either genetically removed either alone or were depleted together with CD103+CD11b− DCs14, 15, 46, 47 homeostatic generation of IL-17A+ Th17 cells was reduced and mice did not develop colitis spontaneously." (PMID 28276457, 2017). "Furthermore, it has been recently reported that a novel subset of helper CD4+ T cells producing IL-17A, namely Th17 cells, is involved in progression of DSS-induced colitis, although an IL-17-mediated protective effect on the Th1-type colitis model has recently been reported." (PMID 24686517, 2014). "This hypothesis is supported by studies performed by Leppkes and colleagues showing that transfer of IL-17A-, IL-17F-, or IL-22-deficient T lymphocytes into RAG1-null mice induces severe colitis that is indistinguishable from that caused by wild-type cells." (PMID 22082127, 2011). "A recent study in mice showed that colonic immunopathology driven by Red 40, and IL-23 may not actually depend on these classical TH17 responses; as IL-17A and IL-17F blockade did not prevent colitis development in mice that conditionally expressed IL23 in CX3CR1-positive myeloid cells." (PMID 38179052, 2023). "Interestingly, the adoptive transfer of T cells deficient in RORγt failed to induce colitis, whereas recombinant IL-17A administration induced severe colitis in mice transferred with RORγt knockout T cells, suggesting a crucial role of Th17 cells in the pathogenesis of colitis." (PMID 37239894, 2023). "Indeed, we found that IL-17A-producing Th17 cells within colonic LP increase in the absence of mPGES-1, suggesting that during colitis, a mPGES-1–dependent mechanism regulates Th17 differentiation and expansion and also lymphocyte infiltration into the inflammatory sites." (PMID 34983695, 2022). "Therefore, we hypothesized that elevated Il17a and Il1r1 transcripts in colonic Th17 cells may position RORγtS182A mice to develop exacerbated tissue inflammation in response to elevated IL-1β signaling during DSS-induced colitis." (PMID 35294872, 2022). "In contrast, when IL17A and IL17F were neutralized in the presence of IFNγ-producing cells minimal effect on weight loss or histopathological scores was observed indicating that inhibition of Th17 cytokine per se is not sufficient for the protection of colitis induction (data not shown)." (PMID 29416538, 2018). "Both in colitis model and aged Tdrd3fl/fl/Foxp3YFP-Cre mice, we observed apparent up-regulation of IFN-γ–producing TH1 cells but not IL-17A–producing TH17 cells." (PMID 41576154, 2026). "Surprisingly, CD69+CD103− CD4+ TRM cells were the major source of IL-17A and IFNγ in the gut of mice with or without DSS-induced colitis." (PMID 35844584, 2022).
colitis (continued). "In accordance with the higher colitis severity of this model, the numbers of IFN-γ+ and IFN-γ+ IL-17A+ CD4+ cells, but not IL-17+ or IL-10+ CD4+ T cells, in the large intestinal lamina propria were higher in LysoPS-treated mice than in control mice." (PMID 35608941, 2022). "In the current study, we hypothesize that the delay in colitis development between mice that received T cells from WT mice and those that received T cells from Il17a−/− mice was due to the differentiation of ILCs that are involved in chronic colitis in the absence of IL-17A." (PMID 31941937, 2020). "TNBS-induced colitis was significantly aggravated in the TPEN-treated mice, and the production of IL-17A, but not IFN-γ or IL-10, was enhanced significantly in the TPEN + TNBS-treated mice." (PMID 32331308, 2020). "The levels of IL-6, IL-17A, IL-23, TNF-α, and TGF-β1 in the colonic mucosa of colitis mice without treatment were higher than in the DSS + SSP and DSS + 5-ASA groups." (PMID 32581849, 2020). "The differential conversion into IL17A-producing CD4 T cells, however, did not affect the severity, or the kinetics of colitis induction (data not shown)." (PMID 29416538, 2018). "In a murine T cell transfer model of colitis, transfer of Tpl2−/− T cells resulted in reduced proportions of CD4 T cells expressing IFNγ, but not IL-17A, compared to that induced by wild type T cells." (PMID 25781948, 2015). "In the present study we found that DSS-induced colitis was not exacerbated in immune milk-fed mice, although IFN-γ production increased in LP, but IL-17A and IL-4 productions decreased." (PMID 24686517, 2014). "IL-17A was not elevated in BALB/c mice, but in B6 mice, and B6 C3ar-/- had lower IL-17A levels than B6 WT mice after DSS-induced colitis." (PMID 23638016, 2013). "Compared to WT colitis mice, lack of TNF-R1 resulted in significant up-regulation of IL-6, IL-1β, MCP-1, IL-17A levels in the colon tissues." (PMID 23285227, 2012). "We found significantly increased IL-17A+ CD4+ T cells, after DDC+DSS treatment while frequencies of Foxp3+ Treg, and IFNγ+ CD4+ T cells were comparable between DDC treated mice with and without acute DSS colitis." (PMID 38510236, 2024). "Similar to the results of previous studies, digoxin efficiently attenuated the colitis induced by adoptive transfer of CD45RB+ CD4 T cells by downregulating Th17 cytokines and receptors, such as IL-17A, IFN-γ, and IL-23R, but did not influence mucosal TNF-α expression." (PMID 30804707, 2019). "However, the effector CD4+ T cells themselves do not seem to be responsible for the induction of colitis, as their numbers as well as their production of the inflammatory cytokines IFN-γ and IL-17A are significantly reduced." (PMID 28452361, 2017). "In fact, although Il17a was not represented in the microarray, qRT-PCR findings showed an increase in the mRNA levels (data not shown), suggesting the involvement of Th17 cells in rat TNBS colitis." (PMID 18928539, 2008). "As opposed to acute experimental colitis, which is mainly characterized by a Th1 immune response, chronic trinitrobenzenesulfonic acid (TNBS)-induced murine colitis, which is accompanied by intestinal fibrosis, is driven predominantly by IL-17A-producing Th17 cells." (PMID 23834907, 2013).
asthma (928 papers, 2006 to 2026). "Studies have shown that Th17-associated cytokines, including IL-17A and IL-21, are upregulated in neutrophilic and corticosteroid-resistant asthma." (PMID 41601686, 2026). "Elevated airway IL-17A levels are linked to neutrophilia in asthma, though the precise role of IL-17A in asthma or how IL-17A is regulated by IL-18 are not well characterized." (PMID 40777291, 2025). "Previous studies in children and adults have linked IL-17A in the serum and airways to asthma severity." (PMID 40337866, 2025). "Beyond TH2 and TH1 subsets, TH17 cells and their hallmark cytokine IL-17A have emerged as key players in neutrophil-predominant severe asthma phenotypes." (PMID 40732309, 2025). "IL-17A, primarily associated with neutrophilic inflammation, is implicated in severe and steroid-resistant asthma; it enhances proinflammatory mediator production and works with IL-13 to amplify airway inflammation." (PMID 41256924, 2025). "In the pathogenesis of asthma, the activation and proliferation of Th17 cells, and their production of IL-17, particularly IL-17A, are closely associated with the development of neutrophilic and eosinophilic asthma." (PMID 41293155, 2025). "Asthma was associated with the increased expression of pro-inflammatory cytokines, including IL-2, IL-5, IL-13, IL-17A, IL-22, IL-33, and TNF-α, and reduced levels of anti-inflammatory cytokine, IL-10 and adipokine, leptin in the circulation." (PMID 39902293, 2024). "IL-17A production in patients with asthma has been associated with airway hyperresponsiveness and asthma severity." (PMID 39194521, 2024). "A case-control study was conducted to determine the association of rs1805010, a single nucleotide polymorphism in the interleukin 4 receptor α chain, with asthma and immunoglobulin E and IL-17A serum levels in Iranian populations." (PMID 38660682, 2024). "Another interesting result that we achieved in this study was the inverse association of increased serum levels of total IgE and IL-17A in patients with mild, moderate, and severe asthma." (PMID 38660682, 2024). "Dysregulation of IL-17A is closely associated with airway inflammation and remodeling in severe asthma." (PMID 38135684, 2023). "IL-17A is a pleiotropic cytokine and intimately associated with asthma, but its role in respiratory syncytial virus (RSV) infection is conflicting in the literature." (PMID 36793128, 2023). "IL-17 (comprising IL-17A and IL-17F) is a central cytokine in yet another adaptive immune system mechanism linked to asthma’s pathogenesis, particularly in neutrophilic phenotypes." (PMID 37834850, 2023). "Knock-down of lncRNA CRNDE reduced the lung injury caused by the asthma induction, increased the IL-10 content, and decreased the contents of IL-17A and IL-6 considerably while reducing the number of Th17 cells in the spleen." (PMID 36743692, 2023). "This suggests a potential role of IL-17A/NETs in the pathogenesis of asthma exacerbation and associated fibrosis." (PMID 38283037, 2023). "Similar findings were also obtained upon the treatment of NETs with a neutralizing antibody against IL-17A, underlining the pro-inflammatory dynamic of asthma NETs in the fibrotic aspect of HELFs." (PMID 37626601, 2023). "Severe asthma is associated with a subset of T helper cells, called Th17, expressing cytokine IL-17 (also known as IL-17A) (Al-Ramli and others 2009; Park and Lee 2010; Wang and Wills-Karp 2011; Trevor and Deshane 2014)." (PMID 35041516, 2022). "LGWWJX protects obesity-related asthma through mechanisms including the inhibition of the IL-1β/ILC3/IL-17A/AHR axis, anti-inflammatory effects, weight loss, and the regulation of lipid metabolism." (PMID 36051916, 2022). "Seys and colleagues evaluated sputum cytokine mRNA expression in an unselected group of adults with stable asthma, and demonstrated that higher levels of IL-5, IL-17A and IL-25 in the airways were associated with uncontrolled asthma and worse lung function." (PMID 35546400, 2022).
asthma (continued). "IL-17A also induces mucus production and goblet cell metaplasia in lung epithelial cells, a common hallmark for asthma and cystic fibrosis." (PMID 35883573, 2022). "Remarkably, although Th17 responses have been reported to counter-regulate Th2 responses and vice versa, under certain conditions IL-13 and IL-17A appear to act synergistically on the inflammatory response underlying asthma formation." (PMID 35883573, 2022). "Th17 cells have been implicated in non-T2 asthma pathology via the production of IL-17A, IL-17E, and IL-22." (PMID 35454142, 2022). "The unstable and plasticity of Th17 cells, which lead to upregulation of Th2-associated cytokine, was examined in detail using the IL-17A reporter system in the HDM-driven model of asthma." (PMID 36032162, 2022). "It has been found that IL-17A is associated with severe asthma and requires IL-23 receptor (IL-23R) signalling, which is adversely controlled by let-7f microRNA." (PMID 36362795, 2022). "In obese patients with asthma, IL-17 is associated with steroid resistance by dysregulation of GRα and GRβ, while in human bronchial epithelial cells, IL-17A induces glucocorticoid insensitivity." (PMID 35626330, 2022). "IL-17A is an independent risk factor for severe asthma and is involved in obesity-associated asthma and CS-related airway neutrophilia." (PMID 35626330, 2022). "The association between the gut microbiota and obesity-related asthma is supported by the evidence of microbiota influence on immune response via changes in IL-17A, an interleukin released by Th-17 cells crucial in the neutrophilic recruitment." (PMID 33669035, 2021). "Several studies suggest that IL-17A and/or IL-17F are associated with airway inflammatory diseases, such as severe asthma and COPD5,6." (PMID 34075087, 2021). "The elevation of IL-17A (the principal pro-inflammatory cytokine of pathogenic Th17 cells) has been found in severe airway inflammation and asthma." (PMID 34135902, 2021). "IL-17A and Th17 cells have been associated with neutrophilic inflammation and more severe asthma phenotypes, and have been correlated with the exacerbation of inflammation and the severity of airway hyperresponsiveness." (PMID 34381060, 2021). "Our group has previously demonstrated that single-nucleotide polymorphisms (SNPs) in IL-17A and IL-17F gene regions are potentially associated with the development of AR and comorbid asthma in Chinese subjects." (PMID 33810821, 2021). "Specifically, IL-17A levels are upregulated in these individuals and IL-17 polymorphisms is frequently associated with asthma." (PMID 35386975, 2021). "Risk factors for allergy development included IL-9 and IL-17A, cytokines which have been associated with asthma." (PMID 33722194, 2021). "Recent reports have suggested that the cytokines of the IL-17 family are increased in BALF samples from patients with asthma and IL-17A has been predicted to be a risk factor for severe asthma." (PMID 35386975, 2021). "Th17 cells and their canonical cytokines, IL-17A and IL-17F, are key players in the pathogenesis of asthma and are closely associated with the more severe phenotypes." (PMID 32670268, 2020). "This was attributed to elevated circulating Th2 and Th17 cells, along with their associated cytokines IL-4 and IL-17A respectively, at both early and advanced stages of pathology in the apoE−/− mice with asthma." (PMID 32194407, 2020). "Although originally defined as a type 2 (T2) immune-mediated condition, non-T2 cytokines, such as IFN-γ and IL-17A, have been implicated in asthma pathogenesis, particularly in patients with severe disease." (PMID 31445933, 2020). "There is mounting evidence that neutrophilic forms of murine and human asthma are associated with IL-17A (hereafter referred to as IL-17)." (PMID 33643284, 2020). "Recently, it has been reported that PTX3 deficiency enhances interleukin (IL)-17A–dominant pulmonary inflammation in an ovalbumin (OVA)-induced mouse asthma model." (PMID 32938460, 2020).